TNF (tumor necrosis factor)
Diseases named in the same sentence as TNF in open-access papers (continued):
Sharing a sentence is not in itself a finding about the gene and the disease.
tumor (continued). "The proinflammatory cytokines and chemokines, such as tumor necrosis factor α (TNF-α), IL-1, IL-6, and IL-8, produced in microenvironments, have been known to promote tumor development." (PMID 22848663, 2012). "NKp46/NCR1 is an activating receptor involved in the killing of virus-infected, tumor cells and self-cells and in the secretion of IFN-γ and of TNF-α in response to various stimulations." (PMID 22457623, 2012). "TNF-α and IFN-γ play important roles in depressing tumor cell growth and inducing apoptosis of tumor cells." (PMID 22811667, 2012). "Next, an efficacy study was performed, dosing D1(A12) or anti-human TNF-α antibody infliximab at 10 mg/kg q7d, quantifying IGROV1-Luc tumour burden by bioluminescence." (PMID 22792380, 2012). "Tumour cells also release soluble mediators such as VEGF-A (vascular endothelial growth factor-A), TGF-β and TNF-α that act on myeloid and endothelial cells and induce the expression of non-classical chemokines such as the S100 chemokine." (PMID 23905066, 2012). "Hypomethylated genes in the TNF network were cytokines (CCL3, CCL4, CCL7, CCL8, CCL22, IL21, IL17A, EBI3) that can either stimulate or inhibit tumor growth and progression." (PMID 22768131, 2012). "Both SE and EE tumor-bearing mice presented a significant increase in systemic inflammatory markers, including, IL-6, TNF-α, MCP-1, PAI-1 and resistin very likely due to the presence of the tumor." (PMID 23272114, 2012). "To investigate the effects of pardaxin on MN-11 cell functions, we detected TNF-α, IL-1β, and MIP-1α concentrations in serum after treatment of tumor-bearing mice with pardaxin." (PMID 23015777, 2012). "In most of these cells, TNF-α acts as an autocrine growth factor, however in some cell types TNF-α induces the expression of other growth factors, which mediate proliferation of tumours." (PMID 23905066, 2012). "Previous studies demonstrated that the direct recognition of tumor cells, viral infected cells and beta cells by NKp46 (NCR1) lead to killing and to the secretion of TNF-α and IFN-γ." (PMID 22457623, 2012). "IFN-γ, TNFα and TRAIL are soluble molecules and thus should be able to penetrate into the tumor through the blood circulation." (PMID 21264227, 2011). "Curcumin (yellow pigment in the spice turmeric)-loaded PLGA nanoparticles were reported to successfully suppress tumor necrosis factor (TNF)-regulated expression of VEGF, culminating in reduced tumor metastasis." (PMID 21349160, 2011). "It is often a result of inflammatory cytokines (tumor necrosis factor, interferon-γ), coagulation proteins (tissue factor and factor VIII), and pro-coagulants secreted by tumor cells." (PMID 21752274, 2011). "In this study, CD4+ T cells produced GM-CSF at significantly higher levels than TNF-α, IL-4, and IFN-γ in response to tumor lysates." (PMID 21931646, 2011). "By day 7, IFNγ, CSF2, CXCL10, GZMB, PTGS2, TNFα, CD80, CCL22, IL12a, IL13, IL1b, IL6, NOS2, and CTLA4 were significantly upregulated in the tumor-bearing mice bladders and AGTR2 and GATA3 were downregulated." (PMID 22013484, 2011). "The prediction is that if CTLs indeed can secrete IFN-γ and TNFα to sensitize the tumor cells, then combinational therapy of CTL adoptive transfer and TRAIL therapy should exhibit greater anti-tumor efficacy than CTL or TRAIL alone." (PMID 21264227, 2011). "Thereby, TAMs promote the angiogenic switch and neovascularization as well as malignant transition of the tumor cells by secretion of specific pro-angiogenic factors (VEGF, IL-1β, TNF-α, angiogenin, semaphorin 4D), or indirectly through the release of MMP-9." (PMID 21914164, 2011).
tumor (continued). "The incidence of TNFα & IL-1β was further increased in IDC patients in whom disease has relapsed, suggesting that these two cytokines push forward processes of tumor progression and recurrence." (PMID 21486440, 2011). "Coculture of preactivated primary NK cells with VV-infected, UV-irradiated tumor cells resulted in a significant reduction of IFN-γ and TNF-α secretion compared to stimulation by uninfected, UV-irradiated cells." (PMID 21901096, 2011). "In this regard, ITPV has the advantage of persistently inducing IL-12 expression at the site of injection; this is followed by infiltration of TNF-α and IFN-γ producing T cells into the lesions, resulting in tumor suppression." (PMID 22216160, 2011). "Tumor necrosis factor-α and interleukin-6 release was clearly increased by DC incubated with H-1PV-induced SK29-Mel tumor cell lysates (TCL) and was also high with DC-CTL co-cultures incubated with H-1PV-induced TCL." (PMID 22029859, 2011). "Our findings support this possibility because they indicate that TNFα, and to a lower extent also IL-1β, induce EMT properties in the tumor cells." (PMID 21486440, 2011). "Treatment of a HR tumor cell line with IL-1β induced the expression of pro-inflammatory cytokines involved in the innate immune responses, including MCP-1, GM-CSF and TNF-α." (PMID 21978632, 2011). "At day 36, tumor inoculation led to a significant increase in serum IL-17, IFN-γ, and TNF-α levels in ST2−/− mice compared with WT animals (p<0.05)." (PMID 21484786, 2011). "While CTLA-4 blockade did increase IFN-γ production from CD8 T-cells in the vaccine and tumor draining lymph nodes, α4-1BB evoked much stronger increases in IFN-γ, TNF-α, and IL-6 production." (PMID 21559358, 2011). "TNF-α has controversial effects in cancer pathogenesis, including induction of apoptosis or EMT of tumor cells." (PMID 21967801, 2011). "It is generally accepted that CD8 T cells, with the ability to directly lyse tumour cells and to secrete interferon IFN-γ and TNFα, are important T cell components of the adaptive tumoral response." (PMID 21918683, 2011). "M1 cells, when stimulated by LPS or IFNγ/TNF induce production of IL-1, TNF, IL-6, IL-23, IL-12, and IL-10, which can be involved in a DTH response, type 1 inflammation, Th1 responses, promoting anti-tumor activity." (PMID 21281484, 2011). "The effects of TNF-α are widespread and mediated through nearly all of the TNF-α receptors on tumor cells and many other cells." (PMID 21345194, 2011). "COSs could either directly kill pathogen micro-organisms or tumor cells by exerting an immune response, or enhance cytotoxic activity and then inhibit tumor cell production by activating T-cells, NK-cells and some other immune cells through some cytokines such as IL-1 and TNF-α." (PMID 20714418, 2010). "A number of factors are known to contribute to tumor angiogenesis, including VEGF, basic FGF (bFGF), TNFα, and SDF1." (PMID 20087418, 2010). "As macrophages are major cytokine-secreting cells, we next examined the levels of TNF-α and VEGF in tumor microenvironment after different treatments." (PMID 20509975, 2010). "Immunization with survivin minigene was associated with an increased presence of CD8+ T cells in the primary tumor and production of the proinflammatory cytokines INF-γ and TNF-α by systemic CD8+ T cells." (PMID 21197271, 2010). "HBD-3 stimulated the expression of tumor-promoting cytokines, including interleukin-1α (IL-1α), IL-6, IL-8, CCL18, and tumor necrosis factor-α (TNF-α) in macrophages derived from human peripheral blood monocytes." (PMID 20544025, 2010). "Cytokines, such as interleukin-1 (IL-1) and tumor necrosis factor (TNF), can act directly on endothelial cells favoring tumor cell adhesion." (PMID 24281071, 2010).
tumor (continued). "Epithelial NF-κB activation results from the rich abundance of IL1β, TNFα and TLR-agonists in the tumour microenvironment, and IL1β, TNFα and many other cytokines and chemokines (i.e. IL6, CXCL2, CCL2 and CCL20) are transcriptional targets for NF-κB." (PMID 20478049, 2010). "During tumor initiation, TAMs create a favorable environment for tumor growth by secreting epidermal growth factor (EGF), platelet-derived growth factor (PDGF), TGF-β, IL-6, IL-1, and tumor necrosis factor (TNF)-α." (PMID 21437225, 2010). "TRAMP mice were strongly protected against tumor development when vaccinated with PSCA-based DNA, an effect supposedly mediated by CD8+ T cells and expression of the cytokines INF-γ, TNF-α, IL-2, IL-4, and IL-15 within prostate tumors." (PMID 21197271, 2010). "TNFR1 null mice are more resistant to DMBA/TPA-induced tumor development than TNFR2 null mice, which indicates that TNFR1 is the major mediator of TNFα-promoted tumorigenesis." (PMID 21297902, 2010). "In 28 (45.9%) of the patients treated with biologics (27 with anti-TNFα and 1 with anakinra) and in 22 (40.7%) patients in the DMARD group the time since the last tumor diagnosis was less than five years when treatment with the respective agent started." (PMID 20064207, 2010). "A recent study has documented that versican can activate tumour-infiltrating myeloid cells through TLR2 and its coreceptors TLR6 and CD14 and elicit the production of proinflammatory cytokines including TNF-α that enhance tumour metastasis." (PMID 20871832, 2010). "With the tumor progression, this picture changed: IL-10 production increased and IFN-γ and TNF-α release decreased; furthermore, there was extensive fungal dissemination." (PMID 19534779, 2009). "Taken together, our results show that at the outset of tumor progression, BTM group animals produced large quantities of TNF-α and IFN-γ and little IL-10, and they showed fungal clearance." (PMID 19534779, 2009). "Cytokine-treated cells were used to evaluate cell surface phenotype, expression of molecular determinants of lymphoid/NK cell differentiation, secretion of IFN-γ, GM-CSF, TNF-α and CCL3/MIP-1α, and cytolytic activity against NK-sensitive tumour cell targets." (PMID 19712464, 2009). "Since TNFα is known to alter vascular barrier function, we performed Evan's blue assay to assess the effect of GX1-rmhTNFα on tumor perfusion." (PMID 19740430, 2009). "Having shown the involvement of TNF-α acting as a VDA in the initial phase of tumor colonization by S. Typhimurium, the similarity between VDAs and tumor-targeting bacteria in experimental tumor therapies becomes comprehensible." (PMID 19693266, 2009). "Both tumor cell lines successfully inhibited IFN-γ and TNF-α secretion and promoted IL-10 secretion, with the latter, primarily produced by the monocytes, as determined using immunofluorescence and flow cytometry." (PMID 19718269, 2009). "TNFα-triggered tumour cell-derived MIF led to increased macrophage metalloproteinase production rates and facilitated tumour cell invasion." (PMID 19602265, 2009). "Our results showed that at the outset of tumor progression, the mice produced more IFN-γ and TNF-α and less IL-10; they also exhibited fungal clearance." (PMID 19534779, 2009). "852A, 3M-003 and CpG 2006 all induced TNF and LTA expression in B cells, which raises the possibly of inducing anti-tumor activity." (PMID 18652679, 2008). "Lymphotoxin-alpha (LTA), a member of the tumor necrosis factor (TNF) family of cytokines, was initially isolated on the basis of an anti-tumor activity." (PMID 18700950, 2008). "to report our experience with EBV-related neoplasms as well as describing the first EBV-related SMN in the setting of administration of glucocorticoids and the tumor necrosis factor inhibitor etanercept." (PMID 19079588, 2008). "These factors, including TNF-α, IL-1α, IL-1β, VEGF, and fibroblast growth factor 2 (FGF-2), raise leptin levels and promote tumor growth and differentiation." (PMID 19017403, 2008).
tumor (continued). "Previously, tumor cells of SCC from head and neck as well as from oral cavity have been shown to contain the immunoreactivity of TNF-α and TNFRI and II." (PMID 18257926, 2008). "The findings in this study assume importance from the point of TNF-α-TNFR1 interaction in the in vivo milieu in gliomas wherein TNF-α is secreted by the tumor infiltrating macrophages and TNF receptors are abundantly expressed by the tumor cells." (PMID 17565690, 2007). "Identifying whether induction of apoptosis and reduced energy metabolism are connected (via TNF-α or another molecular target) will be an important direction for future investigations, and may prove critical for understanding the anti-tumorigenic benefits of a knockdown in tumor FAS." (PMID 17565694, 2007). "While this seems obvious, studies dissecting the mechanism of T cell-mediated tumor regression have focused on perforin, IFN-γ, TNF and Fas-L." (PMID 18001476, 2007). "The cytokines most often detected in serum and ascites of patients with EOC include TNFα, IL-10, IL-6, CSF1 (MCSF), IL-1, and TGFβ isotypes, all of which can be produced by activated MA or by the tumor cells." (PMID 16824216, 2006). "Tumor necrosis factor (TNF; formerly known as TNFα) and lymphotoxin-α (LTA), originally characterized by their ability to induce tumor cell apoptosis and cachexia, are now considered as central mediators of a broad range of biological activities." (PMID 17062130, 2006). "TAMs produce growth and angiogenic factors such as TNF-a, IL-1 b, IL-8, fibroblast growth factor, VEGF, epidermal growth factor as well as protease enzymes which degrade the tumour ECM." (PMID 17026740, 2006). "IL-12 is a potent inducer of anti-tumor immunity and acts together with IFN-γ and TNF-α in a positive feedback loop." (PMID 15566565, 2004). "More active than FAA, and with a 12-fold higher potency in murine tumour models, DMXAA induces TNF production in cell lines from humans, as well as those from mice." (PMID 12698178, 2003). "Presently, we are testing the antitumour effect of BAb, TNFα, and RT combination in an immunocompetent CEA-transgenic mice transplanted with a syngenic CEA-expressing tumour in which all the effects of the targeted cytokine can be analysed." (PMID 14612914, 2003). "Only the combination of TNF-α and melphalan resulted in a complete tumour response in the BN175 tumour." (PMID 12610519, 2003). "In vitro cytoxicity studies showed no sensitivity (CC531 and BN-175) or only minor sensitivity (ROS-1) to TNF-α, ruling out a direct interaction of TNF-α with tumour cells." (PMID 12610519, 2003). "Among other factors that have been suggested are TNF/TNF-R, TRAIL/TRAIL-R, tumour-derived soluble factors, and reactive oxygen metabolites." (PMID 12698200, 2003). "A possible reason for this is that factors released from tumours activate splenocytes, which then react to DMXAA by releasing TNF, thus inducing endothelial cell apoptosis and reducing splenic blood flow." (PMID 12085190, 2002). "Especially the TNF sensitive tumour cell line WEHI-164 responded in a synergistic fashion to the combination of actinomycin D and TNF." (PMID 11953868, 2002). "Addition of 50 μg TNF to ILP with 5 μg actinomycin D not only resulted in inhibition of the tumour growth, but also in tumour shrinkage." (PMID 11953868, 2002). "Production of TNF-α and IFN-γ prior to surgery were reduced to a greater extent in patients with Dukes' stage C tumours compared to those with Dukes' stage A and B stage." (PMID 10737381, 2000). "An additional anti-tumour effect was demonstrated when L-NAME was added to the synergistic combination of melphalan and TNF (responses increased from 70 to 100%)." (PMID 11027431, 2000). "A synergistic anti-tumour effect of L-NAME is observed in combination with melphalan and/or TNF using ILP." (PMID 11027431, 2000).
tumor (continued). "Lipopolysaccharide (LPS) induced 300-fold higher serum TNF-α than did DMXAA at the maximum tolerated dose, but induced similar amounts of TNF-α in spleen, liver and tumour." (PMID 10360649, 1999). "Monocytes are known to be important mediators of anti-tumour ADCC and are also known to secrete the cytokines tumour necrosis factor alpha (TNF-alpha) and interleukin 1 beta (IL-1 beta), both of which have been shown to bring about tumour cell lysis." (PMID 7669568, 1995). "Two independent studies showed that combined treatment with rHu-TNF and rat IFN-gamma induced significant tumour regression over 4 weeks (P = 0.004, P = 0.005 respectively)." (PMID 2495016, 1989). "In addition, NP-APC11 treatment, in contrast to NP-APC11M treatment, significantly increased the expression of the effector cytokines IFNγ and TNFα in CD8+ T cells, highlighting its role in enhancing the anti-tumor immune response." (PMID 41486293, 2026). "Our results demonstrated that the cytotoxic and anti-tumor activities of CAR-T cells were significantly increased post ITK inhibition treatment through elevation of cytotoxic and effector molecules, such as GZMB, TNF-α and IFN-γ." (PMID 41792111, 2026). "Soluble mediators such as cytokines (IL-6, TNF-α), chemokines (CXCL12, CCL2), and immune checkpoints (PD-L1/PD-1, CTLA-4) further exacerbate the immunosuppressive state of HCC TME, forming a vicious cycle that facilitates tumor immune escape and progression." (PMID 41602547, 2026). "Our findings suggest that rBCG amplifies this effect, as evidenced by the greater prevalence of IFN-γ+ and TNF-α+ CD8+ T cells in both the spleen and tumor microenvironment, highlighting the potential to drive more effective and sustained antitumor immune responses." (PMID 41522339, 2026). "Compared with the PBS group, no notable discrepancy in the expression level of TNF-α in the NIR group, because the temperature change caused by NIR alone was insufficient to kill tumour cells." (PMID 41484054, 2026). "Also, in a murine syngeneic tumor model, inhibition of BRAF signaling enhanced production of IFNγ and TNFα and increased MHC class I and II expression on tumor cells." (PMID 41514118, 2026). "Notably, although TNF-α can induce apoptosis under certain conditions, chronic TNF-α signaling in the tumor microenvironment typically enhances tumor cell survival, proliferation, and angiogenesis via sustained NF-κB/ERK pathway activation." (PMID 41596561, 2026). "Tumor recognition by CAR T cells induces IFN‐γ and other cytokines, activating monocytes/macrophages → this amplifies inflammation through IL‐6, IL‐1, IL‐10, and TNF." (PMID 41207679, 2026). "Pathophysiologically, CAR T‐cell recognition of tumor cells induces a burst of IFN‐γ and other effector cytokines that activate monocytes/macrophages, which then amplify the inflammatory cascade through secretion of IL‐6, IL‐1, IL‐10, and TNF." (PMID 41207679, 2026). "In addition to exerting direct cytotoxic effects through NKG2D-mediated release of perforin and granzyme, NK cells also secrete tumor necrosis factor-α (TNF-α) and interferon-γ (IFN-γ) to recruit T cells and dendritic cells to the tumor site." (PMID 41607548, 2026). "The proposed synergistic photo-immunotherapy strategy could realize 3-fold enhancement in tumor infiltrating CD8+ T cells and over 2-fold increase in serum IFN-γ and TNF-α levels." (PMID 41761325, 2026). "Therefore, E. coli strain MG1655, as a tumor-targeting system, specifically produces TNF-α in CT26 mouse colon tumors, significantly inhibiting tumor growth." (PMID 41602751, 2026). "NK cells, as critical effector cells of the innate immune system, recognize and lyse virus-infected or tumor cells, primarily through the release of cytotoxic granules, and secrete cytokines such as interferon-gamma (IFN-γ) and tumor necrosis factor-alpha (TNF-α) to modulate immune responses." (PMID 41601671, 2026).